FOSL1 (FOS like 1, AP-1 transcription factor subunit)
Synonyms: FRA-1; FRA1; FRA
Tractability: PROTAC: ubiquitination databases record sites on it.
Gene: Protein-coding gene on chromosome 11 (65,892,049 to 65,900,573, reverse strand). Ensembl gene ENSG00000175592.
Subcellular location: Nucleus
Subcellular location (Human Protein Atlas): Nucleoplasm
Pathways (Reactome):
Signal Transduction: NGF-stimulated transcription
Gene Ontology:
Molecular function: protein binding; RNA polymerase II cis-regulatory region sequence-specific DNA binding; sequence-specific double-stranded DNA binding; DNA-binding transcription factor activity; DNA-binding transcription factor activity, RNA polymerase II-specific; DNA binding; promoter-specific chromatin binding; RNA polymerase II transcription regulatory region sequence-specific DNA binding
Biological process: positive regulation of DNA-templated transcription initiation; positive regulation of miRNA transcription; cellular defense response; chemotaxis; integrated stress response signaling; positive regulation of cell population proliferation; regulation of transcription by RNA polymerase II; response to virus; regulation of DNA-templated transcription
Cellular component: nucleoplasm; RNA polymerase II transcription regulator complex; chromatin; nucleus
Genetic constraint (gnomAD): Loss-of-function variants: 12 observed, 20.05 expected, observed/expected ratio (o/e) 0.6, 90% interval 0.38 to 0.97. The upper end of that interval is the gene's LOEUF score, 0.97, which puts it in group 4 of 6, group 1 being the genes least tolerant of losing a copy. Missense variants: 299 observed, 329.13 expected, observed/expected ratio (o/e) 0.91, 90% interval 0.83 to 1. Synonymous variants: 124 observed, 132.57 expected, observed/expected ratio (o/e) 0.94, 90% interval 0.81 to 1.09.
Homologues: Orthologues: chimpanzee FOSL1 (100% identical), macaque FOSL1 (99% identical), guinea pig FOSL1 (93% identical), rat Fosl1 (92% identical), mouse Fosl1 (92% identical), pig FOSL1 (91% identical), dog FOSL1 (90% identical), rabbit FOSL1 (69% identical), zebrafish fosl1a (55% identical), tropical clawed frog fosl1 (54% identical), zebrafish fosl1b (21% identical), Drosophila melanogaster Atf3 (16% identical). Paralogues in human: FOSL2 (53% identical), FOS (50% identical), FOSB (42% identical), ATF3 (21% identical), JDP2 (21% identical), BATF2 (15% identical), BATF (14% identical), BATF3 (14% identical).
Diseases named in the same sentence as FOSL1 in open-access papers:
FOSL1 is named in the same sentence as 201 diseases in open-access papers, as found by Europe PMC text mining. Sharing a sentence is not in itself a finding about the gene and the disease. The quoted sentences say what the papers report.
breast carcinoma (115 papers, 2005 to 2026). "TRPS1, which anticorrelates with FOSL1 in aggressive breast carcinoma (TCGA expression Atlas), encodes for a GATA-type zinc-finger transcription repressor playing cell context-dependent roles." (PMID 37176013, 2023). "While other EMT-related genes (e.g., SNAI1 and VIM) are highly coexpressed, ESR1 (Estrogen Receptor alpha) is one of the top anticorrelated genes, in agreement with the FOSL1-associated mesenchymal features of triple-negative (and basal-like) breast cancers." (PMID 37176013, 2023). "Together, these data provide the first genetic evidence indicating that loss of function of GATA3 in mammary tumor cells activates FOSL1 to promote mesenchymal traits and CSC function, while concurrently repressing FOS to lose epithelial features." (PMID 37353480, 2023). "Certain AP-1 components have been implicated in tumor cell invasion, and in particular FOSL1 has been associated with breast cancer metastasis, EMT and cancer stemness." (PMID 32350443, 2020). "Detectable FOSL1 protein expression in mammary carcinomas was demonstrated to be associated with poor differentiation, Ki67 and cyclin E expression and an oestrogen receptor-negative phenotype." (PMID 16495925, 2006). "On the other hand, PDSs generated from breast cancers with associated lymph nodes (LN) metastasis were characterized by higher expressions of the EMT marker FOSL1 (p = 0.047) and the breast CSC-related gene ALDH1A3 (p = 0.024), when MCF7 or T-47D cell lines were used as reporters, respectively." (PMID 35565301, 2022). "In addition to those genes that encode downstream products of IL-17A/IL-17F signaling transduction, the expression levels of IFNG, FOS, FOSB1, and FOSL1 were also found to be associated with ER status in breast cancer." (PMID 33102239, 2020). "FOSL1 also promotes chemotherapy resistance in various types of tumors, including gliomas, colon cancer, ovarian cancer, and breast cancer." (PMID 41556041, 2026). "Previous studies have identified several FOSL1‐mediated stemness inducers such as IL‐6/STAT3 and SNAI3 in breast cancer, suggesting that drug resistance is induced by the FOSL1‐IL‐6/STAT3‐stemness axis." (PMID 41556041, 2026). "Previous reports have shown that increased FOSL1 activates the IL‐6‐STAT3 signaling pathway either directly or through NLRP3‐mediated inflammation in breast cancer and psoriasis." (PMID 41556041, 2026). "In breast cancer, CAFs can generate exosomes containing miR-4516, which can inhibit the expression of FOSL1, thus indirectly inhibiting the proliferation and invasion of tumor cells." (PMID 40821785, 2025). "In lung and breast cancer cells, PARP7 loss-of-function reduces cell proliferation and survival through downregulation of the transcription factor FRA1 (also known as FOSL1), which inhibits the interferon regulatory factors IRF1 and IRF3." (PMID 40741921, 2025). "FOSL1 is an AP-1 transcription factor that has prognostic value in human solid tumors such as breast cancer, lung cancer, pancreatic cancer, and colon cancer, and its overexpression is associated with tumor progression or reduced patient survival rates." (PMID 40224547, 2025). "Recent research has shown FOSL1 to be a valuable clinical outcome indicator for breast cancer patients who are ER-negative." (PMID 38791400, 2024). "The downregulation of miR-19a-3p results in the accumulation of FOSL1 in TAMs, which in turn promotes the invasion and metastasis of breast cancer cells." (PMID 38791400, 2024). "FOSL1, encoding FRA-1, is overexpressed in most solid tumors including lung cancer, breast cancer, ovarian cancer, prostate cancer, gastric cancer, colorectal cancer, head and neck squamous cell carcinomas, and GBM." (PMID 38856747, 2024). "The FOSL1 gene is responsible for encoding Fos-related antigen 1 (FRA1), which is elevated in breast cancer, colorectal cancer, lung cancer, and various other malignancies." (PMID 38957390, 2024).
breast carcinoma (continued). "It has been reported that the expression levels of FOSL1 in drug-resistant breast cancer cells, specifically MCF-7/ADR and MDA-MB-231/ADR, noticeably increase, leading to the induction of resistance to doxorubicin both in vitro and in vivo." (PMID 38791400, 2024). "Prior research has established a connection between miR-4516 and FOSL1-driven tumor cell proliferation and aggressiveness in breast cancer." (PMID 38930863, 2024). "The significance of FOSL1 as a prognostic factor for patients with ER(+) breast cancer is highlighted, and it is suggested that FOSL1 has distinct roles in breast tumor cells depending on the ER status." (PMID 38791400, 2024). "FOSL1 plays a role in regulating the expression of High Mobility Group A1(HMGA1) mRNA at the transcriptional level by binding to enhancer elements in breast cancer cells." (PMID 38791400, 2024). "For example, FOSL1 has been reported to upregulate the expression of IL-6 in breast cancer cells, which can promote tumor growth and invasion by activating the STAT3 signaling pathway." (PMID 38791400, 2024). "One study found that the overexpression of FOSL1 in breast cancer cells led to increased resistance to the chemotherapy drug doxorubicin, while the downregulation of FOSL1 increased sensitivity to the drug." (PMID 38791400, 2024). "FOSL1 also has other signaling pathways that induce invasion and migration of breast cancer cells, such as the increased expression of integrins αVβ3 and uPAR activating the FAK-SRC-ERK2 signal, leading to increased phosphorylation and activation of FOSL1." (PMID 38791400, 2024). "In another study, it was reported that breast cancer patients who were treated with epirubicin-based neoadjuvant chemotherapy (NCT) showed a significant suppression in the expression levels of FOSL1." (PMID 38791400, 2024). "For example, loss of FOS indicates worse overall survival in patients with breast cancer while increased expression of FOSL1 and JUN family members promotes drug resistance and growth in breast and colorectal cancer cells." (PMID 38385626, 2024). "Recently, the c-MYC-dependent control of FOSL1 in breast cancer has been further characterized by studying the NRG-dependent control of c-MYC stability." (PMID 37176013, 2023). "ZEB1 has been shown to function as a transcriptional activator in complex with other transcription factors, such as YAP and AP1-factors c-Jun and FOSL1 in breast cancer." (PMID 38111531, 2023). "We noticed that a low level of GATA3 and FOS mRNA predicted poor outcomes for patients with luminal A or B and basal-like subtype breast cancers, and high FOSL1 expression also predicted a poor outcome for patients with luminal A subtype breast cancers." (PMID 37353480, 2023). "In breast cancer cells, the Twist- and Snail-mediated induction of FOSL1 results in Fra-1 accumulation, which drives the EMT-associated transition from non-CSCs to CSCs." (PMID 35326630, 2022). "EGFR is known to be the key promoter of multiple cancers (e.g. NSCLC, breast cancer), and FOSL1 has been confirmed to be indirectly targeted by circCRIM1." (PMID 35484574, 2022). "A computational pipeline has recently been developed to identify transcribed enhancers in breast cancer and demonstrated that TFs such as FOSL1 and PLAG1 play key roles in regulating the activities of TNBC enhancers." (PMID 34718356, 2022). "The pathway responsible for the ERK-induced recruitment of c-Myc to the FOSL1 promoter in response to neuregulin (NRG1) has been recently elucidated in breast cancer." (PMID 35326630, 2022). "In breast cancer, a higher FOSL1 expression is often observed in the ER-negative tumors, i.e., the most aggressive and highly malignant breast carcinomas, such as HER2-positive and triple-negative breast carcinomas (TNBC)." (PMID 35163444, 2022). "In breast cancer, different subtypes of breast tumors, including estrogen receptor α (ERα)-positive tumors, discover high expression levels of FOSL1." (PMID 35163444, 2022).
breast carcinoma (continued). "According to immunohistochemical data, FOSL1 can be detected in nearly 100% thyroid, 87% esophageal carcinomas, 67% bladder tumors and 92% breast carcinoma samples." (PMID 35163444, 2022). "In breast cancer cells, FOSL1 expression correlates with mesenchymal features and drives cancer stem cells and the regulation of EMT seems to happen through the direct binding of FRA-1 to promoters of EMT genes such as Tgfb1, Zeb1, and Zeb2." (PMID 34399888, 2021). "Mimicking the tumor microenvironment in vitro, the 4T1 mammary carcinoma cells promoted de novo overexpression of Fosl1 in RAW264." (PMID 34712224, 2021). "It has been recently proposed that a FOSL1 signature including a set of TAN-attracting CKs is activated in Basal B type breast cancer cell lines." (PMID 31991796, 2020). "On the other hand, the prediction of the WA-dependent repression of Fra-1 (FOSL1) transcription factor, is in line with our previous results and the known role of Fra1 in cell proliferation, motility and invasiveness of breast cancer cell lines." (PMID 24498382, 2014). "An oral DNA vaccine directed against FOSL1 has been demonstrated to effectively suppress tumor growth, angiogenesis and metastasis in mice injected with breast carcinoma cells." (PMID 20663135, 2010). "For example, miRNA-130a can reduce the content of FOSL1, and FOSL1 can promote the expression of the tight junction protein Zona occludens 1 (ZO-1) in breast cancer; thus, miRNA-130a can indirectly inhibit ZO-1 through FOSL1 by inhibiting its expression to inhibit tumor metastasis." (PMID 40821785, 2025). "Taken together, the FOSL1/DUSP7/DEA15 axis promotes drug resistance in breast cancer." (PMID 38791400, 2024). "The nuclear oncoprotein FOSL1 is overexpressed in most solid tumors including lung cancer, breast cancer, ovarian cancer, prostate cancer, gastric cancer, colorectal cancer (CRC), head and neck squamous cell carcinomas, and GBM, and has emerged as a prominent therapeutic target." (PMID 37642779, 2023). "By similar approaches, the Fosl1 transgenic expression could shed light on the in vivo cooperation between Fra-1 and K-ras in breast cancer initiation and progression." (PMID 37176013, 2023). "Since AP-1 transcription factor complexes have been shown to play a critical role in the expression of Snail family proteins via multiple mechanisms, we examined the expression of the main proteins that form AP-1 complexes in breast cancer cells, including c-Jun, c-Fos, and FOSL-1." (PMID 37057283, 2023). "Here we demonstrated IL11 inhibition by piR-2158 via competing with FOSL1 in breast cancer cells." (PMID 37153732, 2023). "The well-established FRA-1 pro-invasive activity in breast cancer, in which FOSL1 is overexpressed in the TNBC (Triple Negative Breast Cancer)/basal subtypes, correlates with the FRA-1-dependent transcriptional regulation of EMT (Epithelial-to-Mesenchymal Transition)." (PMID 37176013, 2023). "An example is the EMT gene FOSL1 that has a critical role in cell migration and invasion, and that in primary breast cancer shows increased copy number and mRNA overexpression; it has now been observed to be associated with lymph node metastases in the PDS model." (PMID 35565301, 2022). "The therapeutical potential of FOSL1 silencing has been proven in orthotopic mouse models, in which the shRNA-mediated Fra-1 knockdown suppressed lung metastasis and restored epithelial features of breast cancer cells." (PMID 35326630, 2022). "Notably, the microarray data obtained on a large cohort of breast cancer patients suggest that FOSL1 mRNA levels have a significant inverse correlation with the patients’ survival." (PMID 35163444, 2022).
breast carcinoma (continued). "Moreover, two de novo master regulator–target gene pairs are recurrent across the ten cell lines: FOSL1–FOXA1 in prostate cancer cell lines DU-145 and PC-3 and FOSL1–MTRR in the breast cancer cell line MDA-MB-231 and prostate cancer cell line DU-145." (PMID 28854983, 2017). "In addition to its previously known effects on promoting cell proliferation and invasion, FOSL1 may also impact breast cancer progression by modulating the adhesion of tumor cells to endothelial surfaces." (PMID 38791400, 2024). "Another study revealed that miR-130a inhibits breast cancer cell migration and invasion by targeting FOSL1, a transcription factor that regulates tumor cell proliferation and survival, suggesting that miR-130a may suppress the growth and metastasis of breast cancer cells." (PMID 38114755, 2023). "In addition, high expression of FOSL1 caused by rearrangement of the chromosome band at 11q12 appeared to be associated with desmoplastic fibroblastoma and directly induced MMP-1 and MMP-9 promoter activity in breast cancer progression." (PMID 28049150, 2017). "ZEB1 forms complexes with YAP and AP-1 (FOSL1/JUN), activating tumor-promoting genes and reinforcing EMT, particularly in aggressive claudin-low breast cancer subtypes." (PMID 40572800, 2025). "Basal-like breast cancer exhibits enhanced transcription of miR-221/miR-222, which is driven by the basal-like transcription factor FOSL1 (also known as Fra1)." (PMID 38807590, 2024). "Breast cancer cells, specifically MCF-7 and MDA-MB-231, have high FOSL1 levels, enhancing their proliferative and metastatic ability." (PMID 38791400, 2024). "Most reports on FRA-1 in breast cancer dissemination rely on analyses of lung metastases formed by intravenously injected fully mesenchymal TNBC lines (e.g., MDA-MB-231) subjected to FOSL1 silencing." (PMID 37176013, 2023). "In breast cancer, reducing ENTPD1 activity and adenosine generation prevents A2B receptor activation, reducing metastasis-inducing transcription factor FRA1/FOSL1 expression." (PMID 36233136, 2022). "It has been recently proposed that a FOSL1 signature including TAN-attracting CKs (CXCL8, CXCL6 and CXCL5) is activated in Basal B type breast cancer cell lines." (PMID 31991796, 2020). "In this study, we evaluated the copy number of FOSL1, GSTP1,CCND1 in different subtypes of breast carcinomas, classified accordingto the status of hormone receptors, ER and PR, KI-67, and HER2 protein." (PMID 30816904, 2019). "The FOSL1,GSTP1 and CCND1 genes are located at11q13, a cytoband commonly affected by CNA in breast cancer, with relevantfunction in progression and invasion." (PMID 30816904, 2019). "Finally, powerful prognostic correlations originate from the recent analyses of cooperation mechanisms between FOSL1, ZEB1, and YAP in breast cancer." (PMID 37176013, 2023). "Increased copy number and mRNA overexpression of FOSL1 gene are frequently observed in primary breast cancers, independently and irrespectively of the patients’ lymph node axillary metastatic status." (PMID 37642779, 2023). "For instance, phosphorylation and stabilization of FOSL1 in the estrogen receptor (ER)—negative breast cancer cells occurs due to crosstalk between RAS and PKCθ and involves the protein kinase SPAK1." (PMID 35163444, 2022). "FOSL1 and FOSL2 are reported to co-occupy selective gene targets in breast cancer cells." (PMID 35511484, 2022). "Analysis of the DepMap data of glioma cell lines revealed a correlation between elevated FOSL1 expression and unfavorable TMZ response in GBM, which aligns with recent findings that highlight FOSL1 as a transcription factor involved in oncogenesis and chemoresistance in breast cancer and melanoma." (PMID 41556041, 2026).